TNF (tumor necrosis factor)
Diseases named in the same sentence as TNF in open-access papers (continued):
Sharing a sentence is not in itself a finding about the gene and the disease.
breast carcinoma (continued). "However, interestingly the assembly factors required for the complex IV biogenesis were differentially regulated in the presence of TNF-α in the breast cancer cells." (PMID 33926547, 2021). "Importantly for breast cancer, aromatase—the rate-limiting enzyme for estrogen biosynthesis—is stimulated in the adipose tissue by adipose-derived factors (IL-1β, IL-6, TNF-α, and prostaglandin (PG) E2) as well as liver-derived IGF-1." (PMID 34066392, 2021). "In breast cancer cell lines, TNFα may have a role in both promoting and inhibiting cell growth, suggesting that the signaling pathway through which it contributes to proliferation is MAPK and PI3K/Akt." (PMID 34573003, 2021). "In addition, TNF-α has played a key role in the progression of breast cancer, colorectal cancer and cervical cancer." (PMID 34016788, 2021). "Chemotherapy triggers expression of IL-6 and TNF-α in endothelial cells, fostering a pro-tumor inflammatory microenvironment (IL-6) and conferring chemoresistance to breast cancer cells (TNF-α); at the same time, endothelial cells gain chemoresistance by exposure to bFGF and VEGF present in the TME." (PMID 34439387, 2021). "In many breast cancer cell lines, TNF-α contribute to progression in different ways." (PMID 34944905, 2021). "In human melanoma, colon cancer, breast cancer, and other cancer types, IL-32 can be induced by tumor necrosis factor (TNFα and IFNγ to inhibit cancer development, and its high expression may be related to the therapeutic effect of PD1." (PMID 34414188, 2021). "Previous studies have suggested that aggressive and non-aggressive breast cancer cells show differing susceptibilities to TNF-α-induced tumor responses, including cancer cell migration." (PMID 33816268, 2021). "Furthermore, S1P/estrogen and TNFα induced the opposite biological effects in MCF-7 breast cancer cells." (PMID 33919234, 2021). "Moreover, TNF-α was reported to increase the proportion of breast cancer stem-like cells through NF-κB/HIF1α/Slug, indicative of primary breast tumors with self-renewal capacities that are resistant to cell death." (PMID 33816268, 2021). "Variations of therapeutic KDs might provide benefits for breast cancer by decreasing tumor necrosis factor alpha (TNF-α) and insulin while increasing interleukin 10 (IL-10) and may be a promising adjuvant therapy for various cancers (117, –, 121)." (PMID 33849977, 2021). "Notably, all top 10 items were closely related to cancer-related pathways, such as TNF signaling, breast cancer, small cell lung cancer and others." (PMID 34093635, 2021). "We sought to determine whether IκBα’s role in enabling or limiting NFκB activation is important for tumor necrosis factor (TNF)-induced gene expression in human breast cancer cells (MCF-7)." (PMID 34853340, 2021). "TNFα inhibition can suppress breast cancer growth and metastasis; whether this strategy acts directly on the cancer cells or indirectly on nearby cells in the local microenvironment is not completely clear." (PMID 33968771, 2021). "In determining how the EMT may contribute to immune escape, a study demonstrated that after prolonged exposure of breast carcinoma cells to CTLs, expression to TNF-α or via stable expression of SNAIL was increased." (PMID 34122412, 2021). "To verify this hypothesis, we investigated whether the dynamics of NCOR1 protein levels upon TNFα treatment differed between ER-positive MCF7 breast cancer cells and ER-negative MDA-MB-231 cells." (PMID 34073371, 2021). "The induction of TNF-α activates NF-κβ, which promotes breast cancer development." (PMID 34367982, 2021). "Finally, the study of polymorphisms of inflammatory mediators such as the IL6, CXCL8, and TNF genes deserves attention because it can be helpful in the choice of the proper pain therapy for the postoperative period following breast cancer surgery." (PMID 34685397, 2021). "We treated MDA-MB 231 breast cancer cells with MAPKs inhibitors and then incubated with TNF-α." (PMID 34572567, 2021).
breast carcinoma (continued). "Breast cancer cells can produce and utilize TNF-α to activate nuclear factor (NF)-κB signaling." (PMID 34404457, 2021). "Interestingly, in CD95- or tumor necrosis factor (TNF)-induced apoptosis of human breast cancer cell line MCF7, plectin was shown to be an early binding partner of active caspase 8, which results in cleavage of plectin." (PMID 34571895, 2021). "Finally, lifestyle modifications in BRCA1/2+ breast cancer survivors, including physical activity and diets rich in flavonoids (in fruits and vegetables), revealed decreased TNF-α levels." (PMID 34950252, 2021). "TNF-α increases ROS production, potentially contributing to the initiation of breast cancer." (PMID 34944905, 2021). "However, the decrease in cognitive functions as a result of an increased TNF-α level can be found in other reports, mostly in a group of patients with breast cancer whose case results proved inferior memory functioning." (PMID 34573187, 2021). "TNF-α level is high in tumors of different origin including breast cancer." (PMID 33926547, 2021). "TNF-α plays a pro-tumorigenic role during the breast cancer progression and metastasis." (PMID 34572567, 2021). "Similarly, NF-κB activation by TNF-α increases ICAM-1 expression in breast cancer, which is upregulated to promote metastasis and is associated with more aggressive subtypes." (PMID 34404457, 2021). "Taken together, TNF-α can involve in the initiation and development of breast cancer." (PMID 33517609, 2021). "In both in vitro and in vivo studies, TNF-α has shown potential in breast cancer progression and is considered as one of the most important cytokines in the tumor microenvironment, and is secreted by stromal cells (mainly adipocytes and macrophages) and cancer cells." (PMID 34944905, 2021). "TNFα has been shown to be increased in breast cancer compared with healthy normal breast tissue." (PMID 34359821, 2021). "TNF-α polymorphism was related to colorectal cancer in a meta-analysis of 22 studies and increased TNF-α (also IL-6 and 8) was found in a meta-analysis of breast-cancer." (PMID 33803155, 2021). "CD8+ T cells in breast cancer are predominantly of the effector memory cell subtype, with cytotoxic capacity mediating antitumor immunity, but with the ability to secrete proinflammatory cytokines IL-2, TNFα, and INFγ as well." (PMID 34359821, 2021). "GSDMC was then cleaved by caspase-8 in breast cancer cells treated with TNF-α." (PMID 33634141, 2021). "Additionally, TNF-α-activated MSCs mimicked T-MSCs by promoting tumour growth and breast cancer metastasis to the lung." (PMID 33860061, 2021). "TNFα has been shown to induce epithelial–mesenchymal transition in breast cancer cell lines, and it has been suggested as a prognostic marker for human breast cancer progression." (PMID 34371939, 2021). "This is in line with the conceptual goals of Optimune, as regular aerobic exercise seems to reduce inflammatory markers, such as CRP, TNF-α, and Interleukin-6, and reducing chronic inflammation may improve the prognosis of breast cancer survivors." (PMID 33961667, 2021). "NF-κB reportedly mediated TNF-α-induced Lgals3bp mRNA expression in breast cancer cells." (PMID 33824294, 2021). "Fibroblasts adjacent to mammary tumor cells cannot be differentiated into adipocytes because cytokines, such as tumor necrosis factor α (TNFα) and interleukins 6 and 11 (IL-6 and IL-11), secreted from malignant epithelial cells, suppress their differentiation, and also increase aromatase expression." (PMID 33406787, 2021). "Furthermore, radiation has been found to elevate the expression of TNFα, which is known to facilitate breast cancer cell duplication through NF-kB-dependent pathways." (PMID 33406787, 2021). "Furthermore, neutralizing IL-1ß with anakinra in mice xenografted with triple negative MDA-MB-231 and luminal A MCF-7 breast cancer cell lines reduces the incidence of bone metastases and bone turnover markers expression including TNF-α." (PMID 33203195, 2020).
breast carcinoma (continued). "On the basis of these results, although the TNF-α-induced selective apoptotic cell death in ERα-positive breast cancer cells could be partially analyzed, further in-depth experiments should be carried out to address these plausible and interesting scenarios." (PMID 32455774, 2020). "We suggest that TAZ plays a crucial role in TNF-α–promoted breast cancer stemness and could serve as a promising therapeutic target." (PMID 32019974, 2020). "In addition, TNF-α significantly induces the expression of p100 in several breast cancer cell lines; however, the molecular mechanism for this is unclear." (PMID 32019974, 2020). "Future studies should involve more indicators, especially biomarkers such as leptins, C-reactive protein, and TNF-α, and should have expanded sample size and better study design to better reflect the effect of wearable technology intervention on breast cancer survivors." (PMID 33194634, 2020). "Furthermore, we discuss the use of TNFα blocking strategies as potential therapies and their clinical relevance for breast cancer." (PMID 32391269, 2020). "Some other adipocytokines, such as IL-6 and TNF-α released by activated macrophage, results in inflammation, which could be partly responsible for breast cancer development." (PMID 32600328, 2020). "Here we address the different effects of each compound and also analyze the use of potential biomarkers in the selection of patients who would benefit from a combination of TNFα blocking agents with HER2-targeted treatments to prevent or overcome therapy resistance in breast cancer." (PMID 32391269, 2020). "In breast cancer, long-term administration of probiotic strain Lactobacillus plantarum LS/07 has shown immunomodulatory effects such as reducing tumor necrosis factor (TNF)-α and increasing Cd4(+) T-cells." (PMID 32527332, 2020). "The use of TNFα blocking agents for treating breast cancer has been poorly explored." (PMID 32391269, 2020). "Conversely, human breast cancer cells treated with 1,25(OH)2D showed decreased proliferation, in part induced by the reduced TNF-α and IL-1β synthesis, by demonstrating that even drastic deregulation of immune modulators may contribute to cancer progression." (PMID 32560347, 2020). "In metastatic cancer such as prostate and breast cancer, cancer cells in the bone marrow produce cytokines such as tumor necrosis factor α (TNFα), interleukin 6 (IL6), and vascular endothelial growth factor (VEGF) that can trigger recruitment and subsequent differentiation." (PMID 33086479, 2020). "Our findings demonstrated that chronic exposure to pesticides impairs the systemic cytokine production in breast cancer patients, which leads to lower levels of both TNF-α and IL-1β under specific clinicopathological conditions, when compared to the unexposed group." (PMID 32984049, 2020). "Furthermore, the interference of STAT3 (the transfection of si-STAT3) in linc00514-OVE breast cancer cells elevated the mRNA levels of TNF-α, NOS2, and IL-6, and reduced the expression of Arg-1 at both mRNA and protein levels." (PMID 32943090, 2020). "In this regard, preclinical studies in breast cancer have suggested that TNFα promotes tumor growth in vivo and could be considered a therapeutic target." (PMID 32256215, 2020). "Transcriptomic pathway analysis performed on the most potent serotonin modulator (triflupromazine) demonstrates selective down regulation of multiple cell cycle pathways and upregulation of tumor necrosis factor (TNF) signaling pathways in the most sensitive breast cancer cell type." (PMID 31757681, 2020). "In addition, adipocyte-derived conditioned media induced phosphorylation of AKT and mTOR and upregulated the expression of target genes of the PI3K-AKT-mTOR pathway including IL6, IL1β, IL1α and TNFα in breast cancer cells." (PMID 32201525, 2020).
breast carcinoma (continued). "In present case-control study we have also tried to correlate the role of TNF-α -308G /A and TNF-β +252 A/G in Breast Cancer susceptibility by ER, PR and Her2 status and the relationship between genotypes and clinicopathological characteristics of Breast Cancer." (PMID 32102503, 2020). "TNFRSF8 is a tumor necrosis factor with unclear contributions to breast cancer." (PMID 33216733, 2020). "The tumor necrosis factor-alpha (TNF-α)/NF-kappaB/Snail pathway is one of the critical molecular pathways in breast cancer and is involved in many activities related to the tumor cell, including epithelial-mesenchymal transition, proliferation, angiogenesis, invasion, and metastasis." (PMID 33575207, 2020). "Western blotting of the TNFα pathway could be used in future to further validate the effect of miR-143 to breast cancers." (PMID 32370060, 2020). "We found that among the four human breast cancer lines tested, the combination of MK-2206 and Th1 cytokines (IFN-γ and TNF-α) caused greatly enhanced cell death compared with either treatments alone, and this death occurred through an apparent apoptotic mechanism." (PMID 32774769, 2020). "Furthermore, TNF-α is described to be elevated in cats with mammary carcinoma, being positively correlated with serum CTLA-4 levels, as in humans." (PMID 32481540, 2020). "Besides, Li and colleagues also found that APS induced breast cancer cells apoptosis by activating macrophages to release Nitric Oxide (NO) and Tumor Necrosis Factor-α (TNFα)." (PMID 32431616, 2020). "The effects of TNF-α exposure on breast cancer cell lines remain rather contradictory." (PMID 33123472, 2020). "Similarly, cytokines expression, including upregulation of TNF-α expression, leads to enhanced breast cancer cell killing)." (PMID 32466253, 2020). "TNFα signaling pathway regulates metastasis in breast cancer through several mechanisms." (PMID 32986377, 2020). "Interestingly, the dormancy inducer DEC2, which was found equally upregulated in BT474‐Var1 and BT474‐Var4, activates antiapoptotic signaling in breast cancer cells, and its expression appears to be regulated by TNFα/NFκB." (PMID 32392629, 2020). "Meanwhile, the overexpression of linc00514 in breast cancer cells inhibited the THP-1 mRNA levels of TNF-α, NOS2, and IL-6, which are M1 polarization markers of macrophages, while it promoted the expression of Arg-1 at both mRNA and protein levels, which is a M2 polarization marker." (PMID 32943090, 2020). "Therefore, present study investigates the association of TNF-α -308 G/A and TNF-β +252 A/G and the clinical features with Breast cancer patients." (PMID 32102503, 2020). "TNF-α expression has been studied in breast cancer response to therapy." (PMID 33292267, 2020). "A previous study showed that TNFα promotes the DOX-induced apoptosis of breast cancer cells." (PMID 32225068, 2020). "Our hypothesis is also supported by the findings of other studies indicating the efficacy of Etanercept, a soluble receptor, to capture and neutralize circulating TNF-α in breast cancer treatment." (PMID 32883235, 2020). "In the late stages of breast cancer also, c-Met promotes metastases by having vascular reprogramming and inflammatory cytokine upregulation, inflammation-related cytokine tumor necrosis factor-alpha (TNF-α) in tumor invasion." (PMID 33142939, 2020). "Mechanisms of TNFα-induced therapy resistance in breast cancer." (PMID 32391269, 2020). "In addition to TRAIL, strong synergy was also observed between SMs and TNFα in various cancer cell lines, such as glioma, breast cancer, lung cancer, and so on." (PMID 32325691, 2020).
breast carcinoma (continued). "All these facts show that TNFα plays a critical role in luminal breast cancer, inducing tumor promotion, proliferation, survival, progression and metastasis, and that it can be an attractive target for potential new therapies to enhance patients' successful outcome." (PMID 32391269, 2020). "Likewise, we observed that the TEM of breast cancer cells in the presence of TNF/IFN and Tβ4 was blocked by P4D." (PMID 31650345, 2020). "In this contest, it has been reported that breast cancer-secreted exosomes stimulate NF-κB activation in macrophages resulting in the secretion of pro-inflammatory cytokines such as IL-6, tumor necrosis factor alpha (TNFα), Granulocyte colony-stimulating factor (GCSF) and CCL2." (PMID 32764376, 2020). "Human mast cells induce apoptosis of breast cancer cells through tumor necrosis factor-α (TNF-α)." (PMID 32595638, 2020). "Furthermore, the TNF-α-induced apoptotic death of breast cancer cells was also visualized using BrdU-Red TUNEL staining." (PMID 32455774, 2020). "Attractor analysis (i.e. the steady state of the system) demonstrated that when breast cancer cells were modeled alone and treated with Etanercept (i.e. Macrophage and TNF-α state were set to 0), proliferation and cell survival were found in the OFF state while apoptosis was in the active state." (PMID 32883235, 2020). "In addition, TNF-α expression levels are significantly positively correlated with recurrence and malignance in these breast cancer patients." (PMID 32019974, 2020). "However, the effect of brazilin on CXCL3 signaling related to TNFα in metastatic breast cancer remains elusive." (PMID 32986377, 2020). "Moreover, serum IL6, IL8, and TNFα are related to an advanced stage and metastatic status of breast cancers, whereas IL6 and IL8 are most favorable for prognosis." (PMID 31398937, 2019). "Among the factors secreted by macrophages, CCL18 was reported to have strong effects on breast cancer progression whereas macrophage-secreted IL-1β, TNF-α, and CCL5 were previously suppressed by IL-32θ; thus, mRNA expression levels of these factors were measured." (PMID 31126309, 2019). "Moreover, it has been shown that TNF-α--NF-κB axis is related to the invasiveness and malignant behavior of breast cancer cells." (PMID 30642295, 2019). "Similarly, in a DMBA-induced mammary carcinoma rat model, melatonin treatment increased apoptosis as observed by the upregulation of tissue caspase-3 activity, TNF-alpha and the percentage of DNA fragmentation." (PMID 30700756, 2019). "Thus, nanoparticles are expected to serve as an efficient tool to deliver therapeutic agents (including TNF antagonist) or even to directly regulate TNF-TNFR2 interactions in breast cancer cells." (PMID 31239840, 2019). "Moreover, considering that both calcitriol and TNF-α inhibited cell proliferation in the three established breast cancer cell lines used in this study, we decided to evaluate the combination of both compounds on cell growth." (PMID 31093512, 2019). "Violacein was also shown to induce TNF-α gene expression in human breast cancer cells." (PMID 31541142, 2019). "Herein, we determined whether TNFα could induce GM-CSF production in MDA-MB-231 breast cancer metastatic cells, and if so, which signal transduction pathway(s) were involved." (PMID 31581558, 2019). "Moreover, many studies have shown that TNF-α expression results in the induction of multiple autophagy markers in breast cancer cells, lung cancer cells, and Ewing’s sarcoma cells." (PMID 31540489, 2019). "TNF-α is another proinflammatory mediator with dual effects in breast cancer." (PMID 31093512, 2019). "Indeed, a previous study demonstrated that after the treatment with TNF-α around 90% of breast cancer cells lines translocated p65 to the nucleus and that this activation correlated with the induction of migration of non-migratory cells." (PMID 31602271, 2019).